AMBRA1 (autophagy and beclin 1 regulator 1)
Diseases named in the same sentence as AMBRA1 in open-access papers (continued):
Sharing a sentence is not in itself a finding about the gene and the disease.
cancer (41 papers, 2014 to 2026). A tumor composed of atypical neoplastic, often pleomorphic cells that invade other tissues. "Similar to the patients with Cowden/Cowden-like syndrome, Ambra1 cKO mice were susceptible to malignant tumors, some of which contained hotspot mutations in Kras (G12D) and Ctnnb1 (G34E)." (PMID 40734673, 2025). "Survival analysis indicates that patients with high AMBRA1 expression and high cancer-associated fibroblast infiltration have poorer survival rates (p=0.0196)." (PMID 39720719, 2024). "High AMBRA1 expression also indicated worse prognosis in patients with high cancer-associated fibroblast infiltration." (PMID 39720719, 2024). "The cell cycle arrest and increased apoptosis observed in AMBRA1-deficient cells further highlight its importance in maintaining cancer cell viability." (PMID 39720719, 2024). "While its knockout is embryonically lethal in mice, heterozygous Ambra1+/− mice are characterized by pre-diabetic conditions, autism-like phenotype limited to female sex and higher cancer susceptibility." (PMID 37106439, 2023). "AMBRA1 is also associated with cancer development, including EMT, migration, invasion, and metastasis." (PMID 36237336, 2022). "In this study, we used Cancermuts on AMBRA1, allowing to identify putative cancer mutations of interest to be further validated experimentally." (PMID 36243772, 2022). "Future studies need to focus on ascertaining the underlying mechanisms of how AMBRA1 plays opposite roles in different cancer types and figure out the gene context determining different functions of AMBRA1." (PMID 36237336, 2022). "Of note, AMBRA1 deficiency was associated with an increased size and length and a decreased shape factor of FAs, a feature of cancer cells characterized by a faster motility 25,26." (PMID 33953176, 2021). "Alternatively, AMBRA1 may contribute to the growth suppression of cells harboring cancer-associated mutations, which are found even in normal tissues, to maintain homeostasis." (PMID 40734673, 2025). "AMBRA1 decides cell survival or death by maintaining a balance between apoptosis and autophagy and has been shown to be implicated in modulating the sensitivity of cancer cells to anticancer drugs." (PMID 40464146, 2025). "As AMBRA1 is a pivotal autophagy-associated protein, targeting AMBRA1 similarly may be an underlying strategy for cancer therapy." (PMID 36237336, 2022). "The different effects of AMBRA1 in cancers may be due to diverse types and stages of cancer, as AMBRA1 is an autophagy-associated protein and has different roles depending on the gene context." (PMID 36237336, 2022). "Despite the increasing evidence of the functional role of AMBRA1 in cancer stem cell (CSC) properties, the underlying mechanisms remain unknown." (PMID 34769507, 2021). "AMBRA1 may suppress the proliferation of cancer driver mutation-harboring cells." (PMID 40734673, 2025). "We identified several novel roles for AMBRA1 in a range of cellular pathways including cancer signaling pathways such as MAPK, angiogenesis, tissue growth factor signaling, axon guidance, and Wnt signaling." (PMID 42231548, 2026). "AMBRA1 regulates cancer cell migration, and RNA sequencing reveals global gene profiles regulated by AMBRA1." (PMID 40110710, 2025). "AMBRA1 is a multifunctional protein that is involved in many cellular processes, including autophagy, proliferation, apoptosis, transcription and cancer drug resistance." (PMID 40110710, 2025). "Combined with clinical data, the pan-cancer analysis of AMBRA1 was performed to analyze the role of AMBRA1 in STAD." (PMID 39720719, 2024).
cancer (continued). "Given AMBRA1’s diverse cellular functions, its role in cancer development and progression has become a subject of increasing interest." (PMID 39720719, 2024). "Ki67 staining, a marker of cellular proliferation, was substantially reduced in AMBRA1-depleted tumors, suggesting a significant decrease in the proliferative capacity of these cancer cells." (PMID 39720719, 2024). "Emerging evidence has indicated that AMBRA1 affects cancer formation, maintenance, and progression by regulating c-MYC and cyclins, which are frequently deregulated in human cancer cells." (PMID 38542788, 2024). "Ambra1 is considered to be an autophagy and transport protein that plays a role in neurogenesis and cancer cell invasion." (PMID 37225761, 2023). "We showed that SNX29 expression was associated with most genes in most cancers, such as ATG2B, EPG, AMBRA1, and BECN1, in most cancers." (PMID 36829159, 2023). "The activating molecule in Beclin1-regulated autophagy protein 1 (AMBRA1) is an intrinsically disordered protein that regulates the survival and death of cancer cells by modulating autophagy." (PMID 36237336, 2022). "New cancer-related roles for AMBRA1 have emerged over the years, particularly with regard to cell proliferation and tumorigenic potential." (PMID 36243772, 2022). "We applied Cancermuts to the intrinsically disordered protein AMBRA1, a key regulator of many cellular processes frequently deregulated in cancer." (PMID 36243772, 2022). "As previously shown, AMBRA1 is an important factor at the crossroad between autophagy, development and cancer." (PMID 34302498, 2021). "In detail, LC3A/B and Beclin 1 were expressed both in the cytoplasm and in the nucleus of the cancer cells, while AMBRA-1 was preferentially localized in the nucleus, mainly in high grade cases." (PMID 30893939, 2019). "LC3A/B and Beclin 1 were expressed both in the cytoplasm and in the nucleus of neoplastic elements, mainly in high grade cancers; AMBRA-1 was preferentially localized in the nucleus." (PMID 30893939, 2019). "Ambra1 regulates the targeting of active phospho-Src away from focal adhesions into autophagic structures that cancer cells use to survive adhesion stress." (PMID 28362576, 2017). "We found that Ambra1 is critically involved in Src/FAK-dependent cancer cell polarisation and chemotactic invasion." (PMID 28362576, 2017). "As a result, Ambra1 and its interacting partners control cancer cell adhesion, polarisation, proliferation in 3D and chemotactic invasion." (PMID 28362576, 2017). "We conclude that Ambra1 is a FAK scaffold required for FAK-dependent cancer cell phenotypes, most likely by controlling the localisation of active FAK, and its upstream regulator Src, at focal adhesions." (PMID 28362576, 2017). "Notably, AMBRA1 also regulates cyclin D degradation, linking mitophagy to cell cycle control, cancer development, and NDDs." (PMID 40750884, 2025). "Additionally, key mitophagy receptors, such as PINK1, FUNDC1, or AMBRA1, when downregulated genetically, have been shown to sensitize cancer cells to chemotherapy." (PMID 40750884, 2025). "Therefore, AMBRA1 has emerged as a potential target for anticancer treatment and a biomarker for cancer therapy." (PMID 40408472, 2025). "As miRNAs are highly tissue‐specific, they can be employed for the prediction of cancer molecular phenotype; these specific miRNAs may serve as a fundamental method for the diagnosis and management of cancers with AMBRA1 abnormalities." (PMID 40464146, 2025). "In addition to its role in autophagy, recent research highlights the important role of AMBRA1 in cancer cell migration and proliferation." (PMID 40110710, 2025). "For example, autophagy protein 1 (Ambra1) is located at the translational crossroads between autophagy and apoptosis; its expression and distribution regulate the homeostasis between autophagy and apoptosis, thereby altering the efficacy of cancer treatment." (PMID 39682248, 2024).
cancer (continued). "Since spindle orientation is critical for tissue morphogenesis and differentiation, our findings could account for an additional role of AMBRA1 in development and cancer ontogenesis." (PMID 37584777, 2023). "AMBRA1 also regulates neurogenesis and cancer in mammals, suggesting that the function of ATG genes may be conserved." (PMID 38469502, 2023). "The precise role of AMBRA1 in cancer development remains unclear; however, it is clear that disruptions in AMBRA1 regulation in mitophagy are associated with carcinogenesis." (PMID 38067169, 2023). "These miRNAs can regulate chemosensitivity and cancer proliferation by targeting AMBRA1 mRNA." (PMID 36237336, 2022). "Since miRNA is highly tissue-specific and can be used to predict molecular phenotypes of cancers, these specific miRNAs might be used as a basic approach to diagnose and treat cancers of AMBRA1 abnormity." (PMID 36237336, 2022). "While treating these cancer cells with a classic autophagy inhibitor 3-methyladenine (3-MA), they found that the cytotoxicity of cisplatin is impaired, which indicates that AMBRA1-mediated autophagy could enhance the cytotoxicity of cisplatin." (PMID 36237336, 2022). "AMBRA1 is an autophagy-related protein and plays an important role in autophagy induction, so it can enhance resistance or sensitivity to chemotherapeutic agents in cancer treatment." (PMID 36237336, 2022). "In cancer cells, AMBRA1 induces cancer cells to undergo autophagy and inhibits tumor cell apoptosis, and therefore may have a role in drug resistance." (PMID 36614089, 2022). "As c-Myc is well known for its potential role in cancer development and cellular autophagy, it either directly regulates cellular autophagy or indirectly through interacting with other partners such as AMBRA1 regulates autophagy through dephosphorylating c-Myc." (PMID 36072894, 2022). "Up to now, several roles for AMBRA1 and autophagy have been described in human cancer; however, its function in the origin of brain tumours, such as MB, and in lineage-specific mechanisms that could regulate stem cell behaviour is largely unknown." (PMID 34302498, 2021). "However, considering that besides regulating c-Myc degradation and mitophagy, AMBRA1 plays additional functions in cancer cells, it remains challenging to pinpoint the exact contribution of AMBRA1-mediated mitophagy in tumorigenesis." (PMID 31121959, 2019). "We conclude that Ambra1 is a core component of an intracellular trafficking network linked to tight spatial control of active Src and FAK levels, and so crucially regulates their cancer-associated biological outputs." (PMID 28362576, 2017). "Furthermore, Ambra1 belongs to a larger network of proteins within the cancer cells that regulates the location of Src." (PMID 28362576, 2017). "By changing the levels of Src and FAK at focal adhesions, Ambra1 and its other binding partners can control whether the cancer cells are attached to the extracellular matrix or are free to migrate." (PMID 28362576, 2017). "Although the exact role of AMBRA1 in cancer insurgence is still largely unclear, one of the possible mechanisms, proposed by Strappazzon and Cecconi, hypothesizes that AMBRA1 dysregulation in mitophagy might be related to carcinogenesis." (PMID 28512624, 2017). "This could imply that cancers with a high AMBRA1 expression could be more aggressive and have a worse prognosis." (PMID 26423274, 2015). "Structural studies of the AMBRA1 and D-type cyclins have laid the foundation for the development of small molecules targeting the E3 ligase–receptor–substrate complex and provide the potential treatment for diseases characterized by dysregulated cyclin activity, such as cancer." (PMID 40408472, 2025). "However, AMBRA1 is at the crossroad between autophagy and apoptosis and might be a novel prognostic and therapeutic candidate target for cancer therapy." (PMID 36237336, 2022).
cancer (continued). "Having established that Ambra1 and FAK interact with each other and co-localise at focal adhesions, and that they are co-determinants of the intracellular localisation of Src activity, we next addressed whether Ambra1 was required for Src/FAK-mediated cancer-related processes." (PMID 28362576, 2017). "AMBRA1 also regulates Src activity and Src–focal adhesion kinase (FAK)-mediated cancer cell invasion and migration." (PMID 40110710, 2025). "To validate Cancermuts in a cancer study, we focused on the tumor suppressor gene AMBRA1 (autophagy and beclin 1 regulator 1)." (PMID 36243772, 2022). "Thus, AMBRA1 may be a potential target biomarker for future cancer therapeutics." (PMID 36237336, 2022). "Emerging evidence indicates that AMBRA1 can also inhibit cancer formation, maintenance, and progression by regulating c-MYC and cyclins, which are frequently deregulated in human cancer cells." (PMID 36237336, 2022). "Schoenherr and colleagues have recently shown that AMBRA1 is involved in SRC/FAK1-dependent polarization and chemotactic invasion of cancer cells through its interaction with FAK1 and several trafficking proteins, thus regulating adhesion and migration." (PMID 33953176, 2021). "Ambra1 is therefore a novel spatial regulator of the active Src/FAK complex at sites of cell-matrix adhesion, controlling downstream biological effects in cancer cells." (PMID 28362576, 2017). "In this context, therefore, Ambra1 is a scaffold protein that promotes cancer cell phenotypes driven by the Src/FAK pathway, including cancer cell polarisation and chemotactic invasion." (PMID 28362576, 2017). "When FAK is present, Ambra1 forms a complex with FAK and Src and plays a key a role in Src/FAK-regulated cancer cell adhesion, polarisation and invasion." (PMID 28362576, 2017). "When FAK is present, Ambra1 is recruited to focal adhesions, promoting FAK-regulated cancer cell direction-sensing and invasion." (PMID 28362576, 2017). "Among the surviving Ambra1 cKO mice, 60% (three out of five) developed malignant tumors, whereas no tumors were found in the control mice." (PMID 40734673, 2025). "Intriguingly, AMBRA1 has been associated with muscular atrophy, and has been recently shown to modulate the IL6-STAT3 axis, although no direct link to cancer-associated cachexia has been drawn yet." (PMID 31121959, 2019). "Immunostaining for LC3A/B, Beclin-1 and AMBRA-1 were exclusively found in cancer cells, but not in surrounding stromal cells." (PMID 30893939, 2019). "Overall, these data imply a novel role for the autophagic protein Ambra1, and its key interacting partners Dynactin 1 and IFITM3, at the heart of an intracellular trafficking network that, in turn, acts as a ‘spatial rheostat’ for phospho-Src and Src/FAK-mediated cancer processes." (PMID 28362576, 2017).
infection (4 papers, 2019 to 2023). The state of being infected such as from the introduction of a foreign agent such as serum, vaccine, antigenic substance or organism. "The consequences of modification sites on WIPI2 and AMBRA1 are more difficult to predict given less is known with regard to their structural features, so we assessed general autophagy levels following infection." (PMID 31772204, 2019). "Finally, we demonstrate that animals and cells with enhanced ISGylation have increased basal and infection-induced autophagy through the modification of mTOR, WIPI2, AMBRA1, and RAB7." (PMID 31772204, 2019).
neurodegenerative disease (3 papers, 2018 to 2024). A disorder of the central nervous system characterized by gradual and progressive loss of neural tissue and neurologic function. "Dysregulation of these processes are hallmarks of various neurodegenerative diseases and therefore AMBRA1 represents a potential therapeutic target." (PMID 39469809, 2024). "Furthermore, processes that are influenced by AMBRA1 have been implicated in neurodevelopment and neurogenesis, making AMBRA1 activation a potential therapeutic strategy for neurodegenerative disease." (PMID 39469809, 2024).
myopathy (2 papers, 2014 to 2020). A disease of the muscle in which the muscle fibers do not function properly. "Similarly, AMBRA1 deletion results in a severe myopathy with loss of muscle fibers, sarcomere disorganization, and mitochondria alterations." (PMID 33363161, 2020). "Depletion of zebrafish Ambra1 proteins results in abnormal locomotor activity and a severe myopathy characterized by irregular myofiber orientation and highly disorganized sarcomeres, suggesting a role for Ambra1 in muscle development." (PMID 24922546, 2014). "AMBRA1 interacts with Tripartite motif-containing 32 (TRIM32) that is crucial as well, and indeed its deletion causes myopathy with neurological complications, both superimposable with the phenotype observed in patients with limb-girdle muscular dystrophy 2H (LGMD2H)." (PMID 33363161, 2020).
neurodevelopmental disorder (1 paper, 2018). A behavioral and cognitive disorder with onset during the developmental period that involves impaired or aberrant development of intellectual, motor, or social functions. "Together, these findings identify an Ambra1-dependent mechanism that drives inhibition/excitation imbalance in the hippocampus, contributing to abnormal brain activity reminiscent of neurodevelopmental disorders." (PMID 29488136, 2018).
AMBRA1 also shares sentences with these, for which no sentence is quoted: cutaneous melanoma (2 papers); diffuse large B-cell lymphoma (2); inflammatory bowel disease (2); amyotrophic lateral sclerosis (1); atherosclerosis (1); Atrophy (1); Autoimmunity (1); breast tumors (1); cervical cancer (1); colitis (1); Crohn disease (1); diabetic kidney disease (1); endometrial cancer (1); epilepsy (1); esophageal carcinoma (1); head and neck squamous cell carcinoma (1); Insulin resistance (1); leukaemia (1); mantle cell lymphoma (1); metastatic cancers (1); multiple sclerosis (1); muscular dystrophies (1); neurological disorders (1); neurotoxicity (1); Obesity (1); oropharyngeal squamous cell carcinoma (1); pancreatic ductal adenocarcinoma (1); Parkinson disease (1); retinal ischemia (1); rhabdoid tumor (1).
A further 7 diseases each share a sentence with AMBRA1 in 1 paper.